MIR1233-2 (microRNA 1233-2)
Synonyms: hsa-mir-1233-2
Gene: MicroRNA gene on chromosome 15 (34,528,290 to 34,528,371, reverse strand). Ensembl gene ENSG00000221065.
Homologues: Paralogues in human: MIR1233-1 (100% identical).